KRAS (KRas proto-oncogene, GTPase)
Diseases named in the same sentence as KRAS in open-access papers (continued):
Sharing a sentence is not in itself a finding about the gene and the disease.
colorectal cancer (continued). "Increasing evidence showed that KRAS mutations are closely associated with multiple cancers, including non-small-cell lung cancer, colorectal cancer, and pancreatic cancer, and NRAS mutations are present in melanomas." (PMID 32934956, 2020). "Mutations in the WNT pathway frequently occur in colorectal cancer and have been shown to cooperate with KRAS signaling." (PMID 32524209, 2020). "In colorectal cancer, the KRAS (p.G13D) mutation and KRAS (p.G12D) mutation were observed from two CTCs samples isolated from the same patient." (PMID 31650022, 2019). "Wnt1-LateEx tumor susceptibility is probably influenced by age-related changes that increase the risk of developing Hras1-activating mutations, as is the case for KRAS mutations in colorectal cancer." (PMID 31213486, 2019). "RAS is a ubiquitous oncogene in cancers and is highly active and prevalent in both pancreatic (90–95% KRAS mutations) and colorectal cancers (CRC) (35–40%)." (PMID 31247990, 2019). "‘Find all colorectal cancer models with KRAS G12D mutations and resistance to cetuximab’ will retrieve nine models from one source." (PMID 30535239, 2019). "KRAS mutations are exceedingly common in pancreatic adenocarcinomas and colorectal cancers, while NRAS mutations are more common in melanomas, thyroid cancers, and leukemias." (PMID 31681559, 2019). "Subsequent onset of adenoma progression is induced by a secondary oncogenic KRAS mutation in 50% of colorectal cancers." (PMID 30717152, 2019). "We identified that ARID1A is essential in specific contexts of colorectal cancers and was able to show mechanistically that KRAS-mutated colorectal cancer cells are especially dependent on the presence of ARID1A." (PMID 31217031, 2019). "The results from the dPCR analysis were compared before and after the enrichment assay and demonstrated an increased sensitivity using this approach to detect KRAS mutations in patients with colorectal cancer (CRC)." (PMID 31383871, 2019). "In this study, we aimed to develop a dPCR system for detecting KRAS mutations using plasma cfDNA from colorectal cancer (CRC) patients and to compare the results with NGS analysis." (PMID 31896242, 2019). "RAS genes (NRAS, HRAS, and KRAS) are the most common oncogenes in human cancers with high rates of somatic mutations in pancreatic, lung, and colorectal cancers." (PMID 31835496, 2019). "Several studies have reported that KRAS point mutation is involved in the development of several types of cancer, such as pancreatic and colorectal cancers." (PMID 31217933, 2019). "Patients with KRAS mutated colorectal cancer (CRC) represent a cohort with unmet medical needs, with limited options of FDA-approved therapies." (PMID 31766149, 2019). "Hotspot testing for activating KRAS mutations is used in precision oncology to select colorectal cancer (CRC) patients who are eligible for anti-EGFR treatment." (PMID 31805664, 2019). "In particular, KRAS is frequently mutated in cancers with an average of 22% cancers carrying a KRAS mutation, a frequency that rises to 33–61% in colorectal cancer and pancreatic adenocarcinoma." (PMID 31803176, 2019). "In this context we have developed a viable mouse model of colorectal cancer bearing KRAS mutation that authentically serves the purpose of a preclinical model for the human CRC disease." (PMID 31766149, 2019). "For example, ‘find all colorectal cancer models with KRAS G12D mutation,’ will retrieve 68 models from two sources." (PMID 30535239, 2019). "For example, in colorectal cancer, KRAS-mutated tumors show increased SUVmax values as compared to KRAS wild-type tumors." (PMID 30868318, 2019). "Beyond the most common hotspot alleles in exons 2 and 3, mutations in exon 4 of KRAS, including K117 N and A146T, have also been found in patients with colorectal cancer." (PMID 30971271, 2019).
colorectal cancer (continued). "A systematic analysis of preclinical data for a failed phase III trial of selumetinib combined with docetaxel in lung cancer suggests potential indications in pancreatic and colorectal cancers with KRAS mutation." (PMID 31602313, 2019). "DHA, which is the oxidized product of AA, induces cell death in colorectal cancer carrying KRAS and BRAF mutation by deactivating glyceraldehyde 3-phosphate dehydrogenase." (PMID 30903981, 2019). "The KRAS G12S mutation has been reported to occur in 4.9%–5.7% of colorectal cancer samples harboring mutations in the KRAS gene." (PMID 31816869, 2019). "Demuth and colleagues compared KRAS mutation status of 28 patients with metastatic colorectal cancers between cfDNA and matched tumour samples with targeted sequencing and ddPCR, yielding a concordance rate of 79% and 89% for each method, respectively." (PMID 31817150, 2019). "Primary colorectal cancers frequently harbor somatic mutation of KRAS (~40%), BRAF (~10–15%) and PIK3CA (~10–20%)." (PMID 31769426, 2019). "This study aims to show the effectiveness of KYA1797K, a small molecule which revealed anti-cancer effect in colorectal cancer by destabilizing Ras via inhibiting the Wnt/β-catenin pathway, for the treatment of KRAS-mutated NSCLC." (PMID 30679620, 2019). "Several studies have indicated that MEK inhibitors can suppress the proliferation of colorectal cancer cells harboring KRAS or BRAF mutations in vitro and in vivo." (PMID 31769426, 2019). "Some specific RAS mutations show high prevalence in particular tumor types, with the KRAS G12D mutation found in 44% of colorectal cancers and 39% of pancreatic cancers, while 59% of non-small cell lung cancers harbor KRAS G12C mutations." (PMID 31878223, 2019). "The mutations in BRAF and KRAS oncogenes which have been found in approximately 10–20% and 35–42% of sporadic colorectal cancers respectively, has been shown to contribute to the up-regulation of COX-2." (PMID 31108984, 2019). "In colorectal cancer, the concordance of KRAS mutation is 56.10% (92/164), and the concordance of BRAF mutations 46.15% (6/13)." (PMID 31650022, 2019). "PI3K activation plays a central role in the acquired resistance to the combination of anti-EGFR and MEK-inhibitor in KRAS mutated colorectal cancer cell lines." (PMID 30691487, 2019). "We have successfully developed a viable animal model of KRAS mutated colorectal cancer with tamoxifen inducible tumors harboring KRAS and APC mutations." (PMID 31766149, 2019). "Our model includes mutations in APC and KRAS, and therefore represents the most common genetic alterations detected in human colorectal cancer specimens." (PMID 31766149, 2019). "mTOR upregulates asparagine biosynthesis via enhancing expression of the asparagine synthetase (ASNS) in colorectal cancer cells with KRAS mutations." (PMID 31817676, 2019). "Our work suggests that this interaction is especially relevant in KRAS-mutated colorectal cancers, where an attenuation of the MEK/ERK pathway mimics the effects of ARID1A loss in these cells." (PMID 31217031, 2019). "Intratumor KRAS mutation heterogeneity and inhomogeneous distribution over the tumor tissue were observed in colorectal cancer and prostate cancer." (PMID 30368666, 2019). "SERPINE2, a member of the serine protease inhibitor nexin superfamily, contributes to the invasion in solid tumours and more specifically in colorectal cancers bearing KRAS or BRAF mutations." (PMID 30651148, 2019). "In KRAS mutation-driven colorectal cancer, RAD51 has been reported to be transcribed by the KRAS downstream target MYC and to participate in the irradiation-induced DNA damage response and repair." (PMID 31889908, 2019). "Colorectal cancer patients with tumors harboring KRAS mutation are excluded from receiving the otherwise beneficial therapy of anti-EGFR monoclonal antibodies, and currently have no alternate FDA-approved treatment options available." (PMID 31766149, 2019).
colorectal cancer (continued). "Activating mutations in KRAS frequently occur in colorectal cancer (CRC) patients, leading to resistance to EGFR-targeted therapies." (PMID 31133691, 2019). "Landmark examples are the detection of T790M mutation in NSCLC treated with anti-EGFR, the early detection of emergence of KRAS mutations in colorectal cancer and the detection of mutations reverting sensitivity to PARP-inhibitors in prostate cancer." (PMID 35582141, 2019). "Somatic KRAS mutations are found at high rates in leukemia, colorectal cancer, pancreatic cancer and non-small cell lung cancer (NSCLC)." (PMID 30971271, 2019). "Mutations in either KRAS or BRAF drive colorectal cancers and predominate complementary pathways from EGFR that converge on FOXO3a." (PMID 30478887, 2019). "In colorectal cancer, increased activity in AP-1 is linked to KRAS mutation, MSI-activation of Wnt/β-catenin pathway and truncated APC gene." (PMID 31108984, 2019). "This feature has been investigated in an adenomatous polyposis coli (APC)-deficient mouse model where mutations of KRAS were able to promote the development of colorectal cancers, while NRAS mutations were ineffective." (PMID 31803624, 2019). "In cancer management, targeted therapy based on genetic data is widely applied (e.g., cetuximab for KRAS wild-type colorectal cancer, dabrafenib for cancers with V600E BRAF mutation)." (PMID 31167397, 2019). "The most frequent level 1 variants detected were identified in KRAS (colorectal cancer), EGFR (lung cancer), and BRAF (melanoma)." (PMID 30658646, 2019). "In summary, this study demonstrated that overactivation of Akt is associated with MEK inhibitor resistance in colorectal cancer cells harboring KRAS or BRAF mutations and that Akt inhibitor overcame MEK inhibitor resistance." (PMID 31769426, 2019). "Although some of the trials are aimed at enriching a certain molecular subgroup (e.g., MGMT methylation in glioblastoma trials, mutated Kirsten RAS (KRAS) in colorectal cancer), these markers are of important prognostic value of the disease of interest." (PMID 31336983, 2019). "According to statistical analysis of the COSMIC database, colorectal carcinoma cells contain high rates of the gene mutation of KRAS (34%), PIK3CA (14%) and BRAF (10%), the major downstream signaling molecules of EGFR." (PMID 31367332, 2019). "In general, extreme KRAS community scores indicate the presence of mutant, constitutively active KRAS, with pancreatic and colorectal cancers very likely to acquire such mutations due to inherent tissue‐specific cancer biology." (PMID 30573688, 2018). "Greater than 90% of PDAC carry KRAS mutations (with a relatively high mutant allele specific imbalance) and the mutation frequency in lung and colorectal cancer are approximately 30–50% and 40–50%, respectively (COSMIC database)." (PMID 29851957, 2018). "The KRAS gene has a high mutation rate in patients with colorectal cancer and lung cancer, and confers the resistance to epidermal growth factor receptor (EGFR), tyrosine kinase inhibitors (TKIs), and EGFR monoclonal antibody agents." (PMID 30080912, 2018). "The fact that intratumor heterogeneity arises at a premalignant stage from the convergence and admixtures of multiple crypts harboring different APC and KRAS mutations provides fundamental data on the mechanism of the initial evolution of colorectal cancers." (PMID 29652830, 2018). "With this in mind, we provided DHA at concentrations equal to those detected in human plasma and treated colorectal cancer stem-like cells harboring KRAS mutation." (PMID 29619114, 2018). "For example, colorectal cancer harboring KRAS mutation shows the resistance to cetuximab, an EGFR monoclonal antibody." (PMID 30497501, 2018). "For colorectal cancer, the mutation status of KRAS and BRAF in is critical for directing choice of therapy." (PMID 29423054, 2018).
colorectal cancer (continued). "There are some evidence that PIK3CA mutations associated with activation of KRAS- BRAF mutation occurring in colorectal cancers." (PMID 30774815, 2018). "Approximately one third of colorectal cancer patients have a point mutation in their KRAS gene, which causes constitutional activation of the RAS signaling networks." (PMID 30279379, 2018). "We applied this instrument in colorectal cancer diagnosis for detecting KRAS mutation status by polymerase chain reaction-restriction fragment length polymorphism (PCR-RFLP) method." (PMID 29379053, 2018). "A critical role in the resistance to treatment in patients with lung, pancreatic and colorectal cancer is played by continuous activation of the Ras/MAPK pathway because of mutations in codon 12 of the KRAS gene." (PMID 29883450, 2018). "G12D mutation is a known driver mutation and drug target in cancer, of which frequency among KRAS-mutated colorectal cancers is 33.5–34.4%6." (PMID 29662108, 2018). "The presence of chemotherapy-resistant colorectal cancer stem cells (CCSCs) with KRAS mutation is thought to be one of the primary causes for treatment failure in colorectal cancer (CRC)." (PMID 29619114, 2018). "For example, perturbations of the KRAS gene community are strongly associated with strong fitness effects in pancreatic and colorectal cancers, but also exhibit apparent effects in cell lines derived from other lineages." (PMID 30573688, 2018). "Baseline and clinical characteristics of colorectal cancer cases by KRAS and BRAF mutation status and matched controls." (PMID 29694444, 2018). "Of note, the small GTPase KRAS (Kirsten rat sarcoma viral oncogene homolog) acts as a crucial central relay in a number of these signalling cascades and is commonly mutated in colorectal cancers." (PMID 30209039, 2018). "To analyze the influence of Fas survival pathways on the EGFR signaling in cancer, we examined the EGF-induced activation of EGFR in two KRAS-mutated, cetuximab-resistant colorectal cancer cells, SW480 and HCT116." (PMID 30127519, 2018). "GSC showed enhanced antitumor activity based on the results of cell proliferation and clonogenic potential in multiple KRAS-mutated colorectal cancer cells such as SW480 (KRASG12V), LS513 (KRASG12D) and HCT116 (KRASG13D)." (PMID 30577618, 2018). "KRAS mutations in colorectal cancer cells are related to inactivation of STAT1 and decreased sensibility of tumor cells to the anti-tumorigenic effects of IFN-γ." (PMID 30235866, 2018). "Another group of colorectal cancers is represented by KRAS-mutated, CIMP-low and MSS: these tumors seem to originate through an alternative pathway." (PMID 29652830, 2018). "Forty-eight percent of 178 Thai colorectal cancer tissues has KRAS mutation detected by highly sensitive commercial assays." (PMID 29879227, 2018). "For example, the mutation rate of the KRAS gene can reach as high as 15–30% in Caucasian patients with colorectal cancer, and only 4–10% in Asian patients with lung cancer." (PMID 30080912, 2018). "It is of note, however, that the in vivo xenograft experiment was carried out with a colorectal cancer line, HT-29, that is wild-type for KRAS and NRAS, but harbors the activating V600E mutation in the BRAF gene." (PMID 30410004, 2018). "A proteomic study of colorectal cancer cells harboring Kras mutation showed an enrichment of KRAS, EGFR, and SRC family kinases in exosomes." (PMID 30261592, 2018). "In the case of colorectal cancer, both type and location of KRAS mutations are known to predict response to EGFR inhibition in colorectal cancer." (PMID 30234014, 2018).
colorectal cancer (continued). "Considering median progression free survival and overall survival in account, this review focuses to identify the most efficient antibody therapy in combination with chemotherapy (FOLFOX-4) in KRAS mutated colorectal cancer patients." (PMID 29484148, 2018). "In our first study, we analyzed the effect of KRAS downregulation which lead to significantly decreased tumor growth in KRAS mutated colorectal cancer xenograft tumors." (PMID 30001368, 2018). "In colorectal cancer cells with mutated KRAS, treatment with cetuximab (anti-EGFR mAbs) or regorafenib (oral multikinase inhibitor) alone does not produce more than 22% of apoptosis after 24 h of treatment." (PMID 30382908, 2018). "This study examined the anti-cancer activity of GSC on G12V (mutation occurring at codon 12)–KRAS driven colorectal cancer." (PMID 30577618, 2018). "Until recently, indications for standard-of-care molecular testing in colorectal carcinomas included testing for KRAS mutational status as a predictor of response to anti–EGFR agents." (PMID 29755687, 2018). "In colorectal carcinoma, KRAS-mutation indicates irresponsiveness to EGFR-targeted treatment and showed high FDG-PET uptake in multiple studies." (PMID 29732009, 2018). "Intratumoral heterogeneity of KRAS mutations was extensively reported in primary colorectal carcinomas." (PMID 29774112, 2018). "Colorectal cancer (CRC) is an aggressive human malignancy with a complex genomic landscape harboring KRAS mutations." (PMID 28398227, 2017). "For example, using KRAS, a frequently mutated gene in colorectal cancer, to query the colorectal cancer network, we associated the gene to its well-known role in Ras protein signaling transduction." (PMID 27836980, 2017). "Among gastric and colorectal cancer patients, most of the patients (83.3%) were mild to moderate differentiated and 6 (33.3%, colon cancer) had concomitant KRAS mutation." (PMID 27906677, 2017). "Candidate dysregulated miRNAs were selected in genome-wide miRNA expression array analysis using a screening set composed of 15 BRAF-mutated and 15 non-KRAS/BRAF-mutated colorectal cancers." (PMID 29115941, 2017). "CEA is used to monitor relapse of colorectal cancer, and checking KRAS gene mutation can assist in diagnosing colorectal cancer." (PMID 28535767, 2017). "The present study compared absolute amounts of KRAS mutated ctDNA and total circulating cell-free DNA (cfDNA) in colorectal cancer (CRC) patients (n=50) from various stages and healthy controls (n=8) by Intplex allele-specific and digital droplet PCR." (PMID 29156792, 2017). "The KRAS mutation was most common in the KRAS-mutant colorectal cancer cohort, with 97% of these patients having a confirmed KRAS mutation." (PMID 28152546, 2017). "Especially in colorectal cancer, however, where the KRAS mutation status is crucial for the decision of anti-EGFR treatment, there is increasing evidence for a paradigm shift." (PMID 28674438, 2017). "Existing large scale molecular profiling analysis notes that PIK3CA H1047R and KRAS mutations appear to coexist in genitourinary cancers and breast cancers when noted, and are less prevalent concurrently in colorectal cancer." (PMID 28781987, 2017). "In the literature, KRAS mutations have been reported in leukaemia, colorectal cancer, pancreatic cancer, and lung cancer." (PMID 28900470, 2017). "To this effect, we decided to investigate the most frequently observed KRAS mutation in colorectal cancer patients, i.e. G12D with a frequency of 33.5 – 34.4% among KRAS mutated colorectal cancers." (PMID 29156792, 2017). "We detected 477 (43%) colorectal cancer patients profiled in COSMIC V73 to have KRAS mutations, reflecting that almost half of CRC patients are not responsive to anti-EGFR antibody therapies." (PMID 28591715, 2017).